RNU6-321P (RNA, U6 small nuclear 321, pseudogene)
Gene: Small nuclear RNA gene on chromosome 11 (125,277,552 to 125,277,657, forward strand). Ensembl gene ENSG00000222844.
Homologues: Orthologues: chimpanzee U6 (99% identical), macaque U6 (93% identical), rat LOC120097301 (84% identical), dog U6 (75% identical), mouse Gm23656 (75% identical), pig U6 (74% identical). Paralogues in human: RNU6-698P (87% identical), RNU6-116P (86% identical), RNU6-1060P (85% identical), RNU6-33P (85% identical), RNU6-47P (85% identical), RNU6-7 (85% identical), RNU6-8 (85% identical), RNU6-831P (85% identical), RNU6-1 (84% identical), RNU6-15P (84% identical), RNU6-2 (84% identical), RNU6-21P (84% identical), and 1287 more.